TNF (tumor necrosis factor)
Diseases named in the same sentence as TNF in open-access papers (continued):
Sharing a sentence is not in itself a finding about the gene and the disease.
Obesity (continued). "Visceral adipose tissue is also resistant to insulin and leptin and is the site of altered secretion of molecules and hormones such as adiponectin, leptin, resistin, tumor necrosis factor and interleukin-6, which exacerbate cardiovascular disease associated with obesity." (PMID 37081416, 2023). "Furthermore, antifungal agents supplement reverse systems inflammation, a causal link between insulin resistance, obesity and diabetes, as indicated by the alleviated plasma TNF-α and LPS level." (PMID 36854740, 2023). "Healthy lifestyle, including leisure time physical activity, healthy diet, and weight loss can improve energy balance and may reduce obesity-related inflammation, such as IL-6, TNF-α, and CRP." (PMID 37764780, 2023). "Moreover, several studies have shown a tight association between TNF-α and insulin resistance in obesity." (PMID 37048349, 2023). "Obesity has been described to be associated with a chronic state of low-grade inflammation characterised by high levels of inflammatory proteins like leptin, interleukin(IL)-6, IL-8 and tumor necrosis factor-alpha (TNF-α) among others." (PMID 37215211, 2023). "Previous studies suggest that increased levels of interleukin-6 (IL-6) and TNF-α may be linked to obesity and insulin resistance, signifying their involvement in ER stress and reduced insulin sensitivity." (PMID 38140341, 2023). "In obesity, excessive lipid deposition in adipocytes leads to increased cell apoptosis and causes increased accumulation of macrophages around dying adipocytes, regarded as crown-like structure, thus secreting TNF-α." (PMID 37266440, 2023). "TNF-α mediated inflammation, obesity, and insulin resistance were associated with DM50." (PMID 36646777, 2023). "While TNF-α levels released by adipose tissues are unknown, the association between obesity and TNF-α and its receptor mechanism is well explained." (PMID 37512149, 2023). "Similarly, obesity causes low-degree inflammation, and visceral white adipose tissues can actively synthesize inflammatory markers, including TNFα." (PMID 36768469, 2023). "Research suggests that patients with high BMI levels may experience reduced efficacy of benralizumab due to systemic inflammation caused by elevated levels of obesity-related cytokines like TNF-α, IL-6, and leptin." (PMID 38053108, 2023). "Obesity and type 2 diabetes are both associated with TNF-alpha." (PMID 37853419, 2023). "Obesity causes mild inflammation and can hasten the development of chronic diseases and their complications by secreting pro-inflammatory cytokines such as interleukin-6 (IL-6), tumor necrosis factor (TNF), and C-reactive protein (CRP)." (PMID 37275644, 2023). "Notably, dysregulation of TNFα signaling has been associated with metabolic disorders such as insulin resistance and obesity in mammals." (PMID 37828911, 2023). "Obesity is associated with an increase in the secretion of adipocytokines, such as TNF-α, leptin, resistin, IL-1β or IL-6, by immune cells as well as adipocytes, which leads to the progress of insulin resistance through a number of processes, including the activation of Ser/Thr kinases." (PMID 36826001, 2023). "It is important to know that obesity is associated with a lower prevalence of clinical remission and higher anxiety and pain, and exercise may reduce tumor necrosis factor-α and possibly augment the response to antagonists TNF-α." (PMID 37373902, 2023). "Moreover, excess myocardial collagen deposition is linked to high circulating levels of IL-6 and TNF-α in patients with obesity and heart failure." (PMID 37383542, 2023). "In studies that induced obesity in rodents, a reduction of plasmatic glutathione dismutase and superoxide dismutase, which are markers of antioxidant enzymes, was observed, associated with high levels of plasmatic TNF-α and IL-6 as pro-inflammatory markers." (PMID 36986038, 2023).
Obesity (continued). "First, retinol-binding protein 4 is enriched in obesity-associated exosome-like vesicles, which further stimulates the differentiation of peripheral blood monocytes into activated M1 macrophages with increased secretion of IL-6 and TNF-α." (PMID 36593475, 2023). "Obesity-associated dysfunctional adipose tissue (AT) also secretes pro-oncogenic factors such as TNFα, IL-6, IL-1β and provides a carcinogenesis-promoting microenvironment for breast cancer development and progression; it is therefore a fundamental factor of postmenopausal breast cancer development." (PMID 36774339, 2023). "Furthermore, increasing levels of inflammatory cytokines like IL-1, IL-6, and TNF-α are associated with obesity, and these cytokines are secreted by the adipose tissue." (PMID 37571429, 2023). "The low-grade systemic inflammation associated with obesity increases periodontal inflammation and promotes bone resorption processes caused by the recruitment of immuno-inflammatory cells and certain cytokines (IL-1β, TNF)." (PMID 37894804, 2023). "Although more relevant data are needed, it seems that TNF-α may mediate, at least partly, the effect of obesity in the progression of NAFLD, including NAFLD-associated HCC." (PMID 37958479, 2023). "Moreover, considering that chronic inflammation is associated with obesity and can further worsen IR, we measured the levels of TNF-α, IL-1β, and IL-6 in visceral adipose tissue." (PMID 37513467, 2023). "Moreover, obesity is linked with inflammatory cytokines such as tumor necrosis factor-alpha (TNF-α), interleukin-6 (IL-6), and monocyte chemoattractant protein 1 (MCP-1), which are particularly higher among individuals with central obesity." (PMID 38162615, 2023). "Meanwhile, chronic inflammation associated with obesity leads to the overexpression of inflammatory adipokines by activated macrophages, such as Interleukin-6 (IL-6) and Tumor Necrosis Factor-Alpha (TNF-α), which are both correlated with cell proliferation and carcinoma migration." (PMID 38068717, 2023). "Obesity can cause the alteration and elevation of many adipokine productions, including leptin, adiponectin, tumor necrosis factor-α (TNF-α), and interleukin (IL)-6, within the adipose tissue, which can lead to chronic low-grade inflammation and, further, immune dysfunction." (PMID 37569879, 2023). "This evidence may be explained by preclinical data demonstrating that obesity and overweight are associated with an increase in inflammatory cytokines (e.g., IL-6 and TNF-), which represent key mediators in psoriasis." (PMID 37049545, 2023). "Furthermore, BC fruit extract repressed obesity-associated M1 polarization of both murine and human macrophages by reducing the expression of pro-inflammatory genes such as TNF-α." (PMID 37110805, 2023). "Therefore, obesity increases circulating TNF-α levels, increasing the risk of breast tumorigenesis related to insulin resistance and IL-6 synthesis." (PMID 37512149, 2023). "Additionally, obesity has the potential to reduce the efficacy of TNF-α inhibitors and increase the risk of liver fibrosis associated with methotrexate." (PMID 36837593, 2023). "Moreover, ILC1s are crucial in obesity-related inflammation, secreting TNF-α, INF-γ and the costimulatory cytokine IL-18; the hallmark of ILC1 is the production of INF-γ because the subset of ILC1 127+ produces only INF-γ." (PMID 37189844, 2023). "Circulating levels of systemic inflammatory mediators, such as interleukin (IL)-1β and tumor necrosis factor (TNFα), are chronically upregulated in AD, while an increased risk for AD is linked to systemic inflammatory conditions such as Type 2 diabetes, obesity, and rheumatoid arthritis." (PMID 37174621, 2023).
Obesity (continued). "One of the most investigated polymorphisms is the −308 G/A (rs1800629) which has been associated with higher serum concentrations of TNF-α as well as with increased susceptibility for obesity, cardio-metabolic disorders (IR, T2D, MetS) and some inflammatory and immune-related disorders." (PMID 36010524, 2022). "In addition to physical exercise, a number of pharmacological therapies have also been developed with promising potential to improve obesity and type-2 diabetes associated immune dysfunction, such as etanercept (TNF-α blockade)." (PMID 35252310, 2022). "Moreover, the development of liver cancer promoted by obesity depends on the production of tumor promoting cytokines IL-6 and TNF, which can cause liver inflammation and activation of oncogenic transcription factor STAT3." (PMID 35422001, 2022). "In addition, TNFα is associated with anxiety secondary to obesity since its pharmacological blockade improves anxiolytic triggers in obese animals." (PMID 35422689, 2022). "It has been assumed that cytokines IL-6, IL-17A, and TNF-α are the major players in the cytokine storm and biomarkers for acute respiratory distress syndrome and mortality in patients with COVID-19 and definite risk factors, for example, obesity." (PMID 35684003, 2022). "These proinflammatory markers may be a direct source or a consequence of obesity, particularly IL-1β, IL-6, and TNF-α, which are associated with chronic and acute inflammation related to obesity." (PMID 36304965, 2022). "The production of pro‐inflammatory adipocytokines including TNF‐α and IL‐6 is upregulated, whereas that of anti‐inflammatory adipocytokines such as adiponectin is downregulated in AT in association with obesity, with such changes contributing to inflammatory changes in MetS." (PMID 35005845, 2022). "As a cytokine largely expressed in adipose tissue, TNF-α is elevated in obesity and may contribute to obesity-associated metabolic disease." (PMID 36387880, 2022). "In addition, obesity causes a pro-inflammatory state with the release of several mediators like TNF- α, IL-6, and IL-1β, promoting tumor growth." (PMID 35937803, 2022). "Strikingly, impairment of HSC function has now been reported to occur prior to the onset of obesity-induced accumulation of adipose tissue CD11c+ macrophages and the inflammation associated with the IL-1β- and TNFα-driven myeloid/lymphoid skewing of BM progenitors." (PMID 36105811, 2022). "Obesity has a strong association with immune cell abnormalities, and adipose tissue produces and releases various adipokines (leptin, adiponectin, resistin and visfatin) and pro-inflammatory cytokines (TNF-α, IL-4, IL-6)." (PMID 36574392, 2022). "Besides, up-regulated and down-regulated ORDEGs were found to be enriched in inflammation-related pathways, such as adipocytokine signaling pathway and TNF-α signaling pathway, which were implicated in several obesity-related biological reactions." (PMID 35712246, 2022). "Moreover, their research on −174G/C polymorphism of the IL-6 gene and obesity in relation to the therapeutic response to TNF-α blockers showed that the polymorphism can be considered a risk factor in the prognosis of psoriasis treatment." (PMID 35330186, 2022). "Obesity is associated with chronic inflammation, which is characterized by increased levels of several pro‐inflammatory cytokines, including interleukin 6 (IL‐6), tumor necrosis factor‐α (TNF‐α) and C‐reactive protein (CRP)." (PMID 35293040, 2022). "Obesity-associated inflammation in the adipose tissue and liver induces an increase in macrophage infiltration and the expression of pro-inflammatory cytokines such as tumor necrosis factor-alpha and IL-6." (PMID 36470993, 2022). "Obesity causes a state of a chronic low-grade systemic inflammation, with elevated levels of certain circulating proinflammatory adipokines, such as TNF-α, IL−6, leptin, plasminogen activator inhibitor-1 (PAI-1), angiotensinogen, and CRP, as well as lower levels of adiponectin." (PMID 36555411, 2022).
Obesity (continued). "Mounting studies have demonstrated that monocyte-derived macrophages are recruited into tissues (particularly into adipose tissue) via C-C chemokine receptor type 2 (CCR2) and secrete inflammatory cytokines such as TNF-α during obesity, thereby causing systemic inflammation and insulin resistance." (PMID 35563728, 2022). "Likewise, low-grade chronic inflammation associated with obesity and the subsequent increase in pro-inflammatory cytokine secretion is associated with insulin resistance, with TNF-α, IL-1β, and IL-6 directly impairing insulin signal transduction." (PMID 35883605, 2022). "In addition, in men with coronary atherosclerosis and obesity, the presence of unstable atherosclerotic plaques in the coronary arteries is directly associated with the level of TNF-α." (PMID 36013196, 2022). "In obesity, oxidative stress linked with alteration of the immune system and with ultimate aberrant cell signaling, stimulated cell growth and angiogenesis is promoted via enhanced inflammatory factors and adipokines (TNF, leptin, IL-1β, and IL-6)." (PMID 35628513, 2022). "Second, elevated levels of TNF- α and IL-6 that have been linked with obesity and type 2 diabetes might impair insulin sensitivity by inhibiting insulin signaling pathways." (PMID 36213511, 2022). "Animal studies have emphasized that obesity is associated with adipose tissue inflammation and oxidative stress in the liver, and certain Lactobacillus strains can reduce the transcription of proinflammatory cytokine genes, such as IL-6, TNF-α and IL-1β." (PMID 36345438, 2022). "It has been shown that in obesity, there is a decrease in the proliferative capacity of T cells, production of interferon gamma (IFNγ) and TNF-α, and increased expression of PD-1, which may be associated with leptin signaling." (PMID 35164764, 2022). "Obesity-associated chronic inflammation is associated with an accumulation classically activated “M1” polarized macrophages (ATMs) in adipose tissues, which are highly inflammatory and secrete pro-inflammatory cytokines like TNFα." (PMID 35039633, 2022). "Leptin, as well as other pro-inflammatory cytokines, such as interlukin-6 and tumor necrosis factor, are increased in obesity and may be linked to cholangiocarcinogenesis because cholangiocytes express their receptors." (PMID 35884542, 2022). "Likewise, some microRNAs are linked to obesity-induced inflammation through pro-inflammatory pathways, such as NF-κB and the pro-inflammatory cytokines TNFα and IL-6." (PMID 36355127, 2022). "It is well known that a decrease of NFATC2 expression is associated with a reduction of the expression of cytokines in T cells, in particular IL-2, IL-3, IL-4 and TNF-alpha; the latter, in particular, is a pro-inflammatory cytokine associated with obesity and insulin resistance." (PMID 35159548, 2022). "A milestone forward in this field was provided by two simultaneous publications that reported independently that obesity was associated with macrophage accumulation in adipose tissue, which was known as the major source of inflammatory mediators (such as TNF-α)." (PMID 35563728, 2022). "Furthermore, after adjusting for sex, age, hypertension, obesity, and IL-10, IL-4, and IL-6 levels, an increased TNF-α level was also significantly associated with sarcopenia." (PMID 36160136, 2022). "The TNF-α gene, in turn, is associated with obesity and insulin resistance, and hyperandrogegism." (PMID 35703718, 2022). "A high-fat diet and obesity are associated with chronic low-grade systemic inflammation and can induce the secretion of proinflammatory cytokines, such as tumor necrosis factor alpha (TNF-α, interleukin-1 (IL-1), and interferon gamma (IFN-γ)." (PMID 35887932, 2022). "Elevated TNF-α has been associated with both obesity and severe cases of COVID-19156." (PMID 35842456, 2022). "Obesity caused alteration of plasma adiponectin, IL-6 and TNF-α in TNBC patients." (PMID 35964108, 2022).
Obesity (continued). "As a result, lower adiponectin levels in obesity may be associated with increased TNF-α production, which directly inhibits pituitary LH secretion." (PMID 35897011, 2022). "Gut microbiota dysbiosis has also been previously linked to obesity and food addiction due to interactions along the gut-brain axis via altered inflammatory signals such as tumor necrosis factor (TNF), interleukin (IL)-6, IL-1 beta, plasma lipopolysaccharide (LPS), and neuroactive metabolites." (PMID 35163046, 2022). "Furthermore, obesity has been identified as a risk factor for developing hepatocellular carcinoma via increased production of IL-6 and TNF." (PMID 35267581, 2022). "It is well known that elevated serum TNF-α and leptin in type 2 DM are associated with obesity." (PMID 35330131, 2022). "In addition, the gut microbiota influenced inflammatory factors by modulating the secretion of inflammatory cytokines, and IL-6 and TNF-α are the biomarkers associated with inflammation and obesity." (PMID 35579462, 2022). "The presence of polymorphisms in the leptin, adiponectin, and TNF-α genes in adult individuals may alter serum adipokine concentrations and predispose obesity." (PMID 35703718, 2022). "The hub genes CEBPD, TP73, ESR2, TAB1, MAP 3K5, FN1, UBD, RUNX1, PIK3R2 and TNF, which might play an essential role in obesity associated type 2 diabetes mellitus was further screened." (PMID 33902539, 2021). "Importantly, obesity—through increased production of selected adipokines, e.g., leptin and TNF-α—is associated with low-grade inflammation." (PMID 34063466, 2021). "Similarly, TNF‐α is a proinflammatory cytokine that exerts lipid metabolism and insulin signaling in adipose tissue, thus its levels are elevated in individuals with obesity and reduced with weight loss." (PMID 33680494, 2021). "The results of the presented research indicate that it may be reasonable to use the assessment of salivary concentrations of TNF-α in the diagnosis of obesity and its associated disorders and diseases." (PMID 34769133, 2021). "As was mentioned in the pathophysiology of obesity, pro-inflammatory mediators, such as leptin, resistin, IL-6, and TNF-α, may cause an adipose tissue dysregulation and a systemic insulin-resistant state." (PMID 34769060, 2021). "As a strong risk factor for many diseases, obesity predisposes the body to a pro-inflammatory state via increased levels of inflammatory mediators such as tumor necrosis factor (TNF)-α, interleukin (IL)-6, leptin, and reduced levels of adiponectin secreted by adipose tissue." (PMID 34576066, 2021). "5-HT3RAs such as tropisetron can reduce hepatic lesions of obesity-associated fatty liver disease in mice by reducing portal vein plasma endotoxin levels, attenuating the increased MyD88 and tumor necrosis factor-α mRNA expression in the liver, and increasing tight junction proteins in the duodenum." (PMID 33967787, 2021). "Thus, FAS/FAS ligand-mediated signaling appears to be more involved in controlling local inflammation in adipose tissue and promoting WAT browning, that is, TNF is associated with obesity via deactivation of thermogenesis." (PMID 34576181, 2021). "Interestingly, clinical and experimental studies have reported elevated levels of inflammatory cytokines—(interleukin-6 (IL-6), interleukin-1beta (IL-1b), tumor necrosis factor alpha (TNFa)—associated with obesity or HFD consumption." (PMID 34067897, 2021). "Obese individuals showed low-grade inflammation because of the increased production of cytokines, C-reactive proteins (CRP), interleukins (IL), tumor necrosis factor (TNF), and lipopolysaccharides (LPS), which in turn resulted in metabolic dysfunction and obesity-linked disorders." (PMID 34359450, 2021). "Indeed, obesity is associated with the increased production of pro-inflammatory cytokines, such as interleukin-6 (IL-6) and tumor-necrosis factor α (TNFα), leading to a low chronic inflammatory state." (PMID 34940598, 2021).